C21orf58 (chromosome 21 open reading frame 58)
Tractability: No criterion of Open Targets' tractability assessment is met for any kind of drug.
Gene: Protein-coding gene on chromosome 21 (46,300,181 to 46,324,460, reverse strand). Ensembl gene ENSG00000160298.
Subcellular location (Human Protein Atlas): Nucleoplasm; Nuclear bodies; Primary cilium transition zone
Genetic constraint (gnomAD): Loss-of-function variants: 26 observed, 23.33 expected, observed/expected ratio (o/e) 1.11, 90% interval 0.82 to 1.54. The synonymous counts are far from expectation, so gnomAD's model fits this gene poorly and the ratio says little. Missense variants: 367 observed, 288.46 expected, observed/expected ratio (o/e) 1.27, 90% interval 1.17 to 1.39. Synonymous variants: 160 observed, 126.36 expected, observed/expected ratio (o/e) 1.27, 90% interval 1.11 to 1.44.
Homologues: Orthologues: chimpanzee C21H21orf58 (98% identical), macaque C3H21orf58 (90% identical), chimpanzee C21H21orf58 (74% identical), mouse 2610028H24Rik (42% identical), rat C20h21orf58 (41% identical), tropical clawed frog c9h21orf58 (33% identical), zebrafish zgc:112416 (33% identical).
Diseases named in the same sentence as C21orf58 in open-access papers:
C21orf58 is named in the same sentence as 8 diseases in open-access papers, as found by Europe PMC text mining. Sharing a sentence is not in itself a finding about the gene and the disease. The quoted sentences say what the papers report.
metastatic tumors (1 paper, 2023). "In general, overexpression of the C4orf46, C9orf40, C17orf67 and C21orf58 gene of thymoma correlates with tumor immune cell infiltration and gene expression levels of C1orf162, C16orf54 and CXorf21 correlate with immune cell infiltration in many primary and metastatic tumors." (PMID 37373333, 2023).
tumor (2 papers, 2023 to 2024). "Consistently, higher expression of C21orf58 protein was detected in most of the HCC tissues compared to adjacent non‐tumor tissues (P < 0.001)." (PMID 38342622, 2024). "Our future plan is to explore the vital role of C21orf58 in tumor immunity." (PMID 38342622, 2024). "Additionally, cell‐derived xenograft experiment indicated that C21orf58 overexpression notably increased the volume and weight of HCC cells formed tumors, attenuated C21orf58 notably decreased the tumor size and weight, which were consistent with the results in vitro." (PMID 38342622, 2024).
C21orf58 also shares sentences with these, for which no sentence is quoted: hepatocellular carcinoma (2 papers); breast carcinoma (1); cancer (1); lung adenocarcinoma (1); thymoma (1); type 2 diabetes mellitus (1).